SIRT6 (sirtuin 6)
Diseases named in the same sentence as SIRT6 in open-access papers (continued):
Sharing a sentence is not in itself a finding about the gene and the disease.
prostate carcinoma (continued). "In this respect, targeting SIRT6 in prostate cancer with engineered exosomes simulates the potential clinical therapeutic efficiency, resulting in lower proliferation rate of tumor and less metastasis area." (PMID 33995674, 2021). "Here, we assess the function and therapeutic value of SIRT6 in metastatic castration-resistant prostate cancer." (PMID 33995674, 2021). "The IHC analysis showed significantly elevated levels of SIRT6 in prostate cancer tissues with high Gleason scores." (PMID 33995674, 2021). "In conclusion, SIRT6 is a novel and promising target in metastatic castration-resistant prostate cancer." (PMID 33995674, 2021). "Owing to the multiple catalytic function and a broad substrate spectrum, SIRT6 seems to promote prostate cancer progression in a diverse and complex way." (PMID 33995674, 2021). "SIRT6-driven prostate cancer displays activation of multiple cancer-related signaling pathways, especially the Notch pathway." (PMID 33995674, 2021). "We also verified this finding in prostate cancer cell lines that overexpression of SIRT6 increased the levels of p-S6, p-S6K, which were downstream of mTOR pathway." (PMID 33995674, 2021). "Consistently, microarray analysis of prostate cancer profiles (GDS2546) in GEO datasets confirmed that SIRT6 mRNA level in metastasis site samples was remarkably increased compared with the normal or primary site tissues." (PMID 33995674, 2021). "The copy number of SIRT6 in metastatic prostate cancer tissues (n=35) was much higher than normal tissues (n=28) and primary site tissues (n=59) in the Grasso Prostate dataset containing 122 human clinical specimens." (PMID 33995674, 2021). "Our study thus provides preclinical evidence for SIRT6 as a novel therapeutic target in high-grade prostate cancer." (PMID 33995674, 2021). "To evaluate the effect of SIRT6 on prostate cancer proliferation and metastasis in vivo, we needed to establish an orthotopic prostate cancer model." (PMID 33995674, 2021). "Overexpression or knockdown of SIRT6 in prostate cancer cells significantly promoted or inhibited migration both in vitro and in vivo." (PMID 33995674, 2021). "Correspondingly, silencing SIRT6 suppressed the downstream molecules of mTOR pathway in both prostate cancer cell lines and in vivo tissue samples." (PMID 33995674, 2021). "Here, our study implicates the pro-metastatic role of SIRT6 in prostate cancer and uncovers the mechanism involved in malignant progression driven by SIRT6." (PMID 33995674, 2021). "Together, targeted inhibition of SIRT6 via engineered exosomes impaired the proliferation and metastasis in prostate cancer." (PMID 33995674, 2021). "As a follow-up study to our previous report that silencing SIRT6 reduced the prostate cancer cell viability, this work has several novel findings." (PMID 33995674, 2021). "In SIRT6-overexpression orthotopic prostate cancer model, the tumor growth was measured by the bioluminescence." (PMID 33995674, 2021). "In prostate cancer, SIRT-3 and SIRT-6 can protect prostate cancer cells from necroptosis and reduce the overall survival." (PMID 34869390, 2021). "The results were confirmed by other prostate cancer cohort (Multi-Institute, Nat Med 2016) from cBioportal which also showed the co-expression of SIRT6 and Hes1/Hey1." (PMID 33995674, 2021). "We expressed the SIRT6 wild type and two SIRT6 mutants (G60A and R65A) in SIRT6 knock-down prostate cancer cells respectively and test their effect on proliferation and migration." (PMID 33995674, 2021). "And the GSEA also showed that SIRT6 activated a variety of signaling pathways important in prostate cancer, among which the Notch pathway showed the highest Enrichment Score." (PMID 33995674, 2021). "To validate our findings, we examined the SIRT6 expression by immunoblots in benign human prostate tissue (n=7) and prostate cancer tissue (n=7), and found higher SIRT6 levels in prostate cancer tissues than those in normal prostate tissues." (PMID 33995674, 2021).
prostate carcinoma (continued). "The microarray IHC analysis also verified that the levels of SIRT6 significantly increased in high stage prostate cancer tissues." (PMID 33995674, 2021). "In summary, these results suggest that SIRT3 and SIRT6 promote prostate cancer progress by suppressing necroptosis-mediated immune response." (PMID 33282964, 2020). "Overall, our study identified that SIRT3 and SIRT6 are key regulators of necroptosis during prostate cancer progression." (PMID 33282964, 2020). "Mechanistically, we found that SIRT3 and SIRT6 promote prostate cancer progress by inhibiting RIPK3-mediated necroptosis and innate immune response." (PMID 33282964, 2020). "The overexpression of SIRT6 observed in prostate cancer cells and downregulation of H3K18Ac suggests that SIRT6 influences prostate cancer development and that it can be a potential target for anti-cancer therapy." (PMID 31121824, 2019). "In contrast, SIRT6 expression is up-regulated in patients with prostate cancers, which is related to chemoresistance and poor prognosis in patients with cancer." (PMID 31128573, 2019). "Moreover, many types of cancer cells, including H460, A549, and prostate cancer cells, have high levels of SIRT6, and inhibiting SIRT6 in these cells results in cell death." (PMID 39940397, 2025). "While reduced SIRT6 expression was observed in colon, liver, pancreatic, and ovarian cancers, where it functioned as a tumor suppressor, elevated SIRT6 expression was demonstrated in prostate cancer, acute myeloid leukemia, multiple myeloma, and osteosarcoma." (PMID 38819446, 2024). "SIRT6 is an important member of highly conserved family of NAD+-dependent histone deacetylase whose overexpression has been evidenced in many cancer types including prostate cancer." (PMID 38802766, 2024). "Furthermore, a recent study reported that SIRT6 promotes the progression of prostate cancer by abrogating necroptosis-facilitated innate immunity." (PMID 36291902, 2022). "In prostate cancer, SIRT6 is overexpressed in prostate tumors." (PMID 35463332, 2022). "This indicates an important role of SIRT6 in prostate cancer, which needs to be fully explored." (PMID 36291902, 2022). "To date, all studies unequivocally portray SIRT6 as a promoter of prostate cancer." (PMID 36291902, 2022). "To determine the role of SIRT6 in prostate cancer, we analyzed the copy number of SIRT6 in the prostate cancer cohorts from the Oncomine database and observed that SIRT6 was highly amplified in prostate cancer tissue samples, especially in metastatic prostate cancer tissue samples." (PMID 33995674, 2021). "Next, we explored the potential function of elevated SIRT6 expression in prostate cancer." (PMID 33995674, 2021). "The GSEA result was verified in prostate cancer cell lines that overexpression of SIRT6 could activate the Notch pathway by upregulating the expression of Notch receptors and ligands." (PMID 33995674, 2021). "The SIRT6 interfering efficiency in subcutaneous tumor model was confirmed by immunohistochemistry and the Ki67 staining of tumor tissues showed that the engineered exosomes suppressed the prostate cancer cell proliferation." (PMID 33995674, 2021). "Finally, we used exosomes modified with a specific aptamer as an efficient siRNA delivery system, which targeted the prostate cancer cells only to silence SIRT6 in vivo." (PMID 33995674, 2021). "Collectively, these results further verified that SIRT6 could promote the proliferation and metastasis of prostate cancer both in vitro and in vivo." (PMID 33995674, 2021). "First, we found for the first time that SIRT6 accelerated the metastasis in prostate cancer." (PMID 33995674, 2021). "Targeting SIRT6 could serve as a promising method for advanced prostate cancer instead of the traditional drugs." (PMID 33995674, 2021).
prostate carcinoma (continued). "The protein level of SIRT6 was slightly higher in aggressive prostate cell lines (PC3M and C42B) compared with the parental cell lines (PC3 and LNCap), indicating SIRT6 may affect metastatic phenotype of prostate cancer cells." (PMID 33995674, 2021). "Considering its significant role in prostate cancer progression, silencing SIRT6 in prostate cancer sites may be pharmacologically interesting, especially for the potential application in metastatic prostate cancer therapeutic strategies." (PMID 33995674, 2021). "The GSEA plots in a Metastatic Prostate Cancer dataset from cBioportal showed that SIRT6 was positively correlated with the cell cycle-related gene Cyclin D1, indicating SIRT6 may promote prostate cancer proliferation." (PMID 33995674, 2021). "On the other hand, SIRT6 inhibition reduced prostate cancer cell viability and increased apoptosis, suggesting that SIRT6 may promote tumorigenesis." (PMID 27777384, 2016). "However, little has been identified about the detailed function of SIRT6 in prostate cancer." (PMID 33995674, 2021). "Thus, we used siRNA to assess whether targeting SIRT6 specifically might be therapeutically effective in prostate cancer." (PMID 33995674, 2021). "Furthermore, to test whether silencing SIRT6 could inhibit prostate cancer cell proliferation and metastatic ability in vivo, the SIRT6-knockdown PC3M-luc and control PC3M-luc cells were used to establish the orthotopic prostate cancer model." (PMID 33995674, 2021). "In bladder and prostate cancer cell lines, E2F1 enhanced cancer cell glycolysis by directly binding to the proximal SIRT6 promoter and suppressed SIRT6 expression, as well as significantly enhanced glucose uptake and lactate production." (PMID 35689245, 2022). "Second, we identified the downstream signals of SIRT6 in prostate cancer by GSEA, revealing a significant enrichment of SIRT6-induced signaling pathway activation signature." (PMID 33995674, 2021). "We measured SIRT6 and Mstn protein levels in the gastrocnemius muscle of athymic mice injected with PC3 cells (human prostate cancer cell line)." (PMID 28928419, 2017). "The absence of SIRT6 significantly inhibits the activation of prostate cancer-related signaling pathways such as the Notch pathway, thereby inhibiting the proliferation and metastasis of prostate cancer cell lines." (PMID 35463332, 2022). "However, it is still unclear how SIRT3 and SIRT6 regulate RIPK1/RIPK3-mediated necroptosis and in turn maintain prostate cancer progress." (PMID 33282964, 2020). "To determine whether SIRT3 and SIRT6 are required for the growth of prostate cancer in vivo, we generated the LNCaP cell line with shRNA of SIRT3 and SIRT6 after doxycycline induction using a lentivirus transduction system." (PMID 33282964, 2020). "While some studies have suggested a tumor suppressor function of SIRT6 in liver and intestinal cancers, others have shown that it has oncogenic properties in prostate cancer and non-melanoma skin cancer." (PMID 29234488, 2017). "Utilizing prostate cancer and bladder cancer cell lines, our data support our hypothesis that E2F1 suppresses SIRT6 transcription and facilities cancer cell glycolysis." (PMID 25816777, 2015). "Here we tested our hypothesis in bladder and prostate cancer cell lines and found that E2F1 could indeed suppress SIRT6 transcription and promote cancer cell glycolysis." (PMID 25816777, 2015). "However, detailed studies on the oncogenic role of SIRT6 in prostate cancer and potential applications by modulating SIRT6 are still lacking." (PMID 33995674, 2021). "The GSEA in Metastatic Prostate Cancer (SU2C/PCF Dream Team, Cell 2015) dataset from cBioportal found that histone deacetylation was enriched in the SIRT6 high expression group, indicating histone deacetylation may be associated with the malignancy development driven by SIRT6." (PMID 33995674, 2021).
pancreatic cancer (33 papers, 2015 to 2025). "In KLF10-deficient pancreatic cancer cells with low SIRT6 levels, LA elevated SIRT6 expression and activity, which led to upregulated glycolytic enzymes." (PMID 34702956, 2021). "In the present context, SIRT6 protein acts as a suppressor of colon tumorigenesis, which suppresses pancreatic cancer through control of the zinc finger protein Lin28b, which drives the growth and survival of SIRT6-deficient pancreatic cancer." (PMID 33510943, 2021). "Increased expression of SIRT6 is associated with favorable prognosis of gastric and pancreatic cancer patients." (PMID 30524965, 2018). "In summary, these findings illustrate the dual nature of SIRT6 in pancreatic cancer: acting as a promoter of metastasis and chemoresistance in some contexts, while functioning as a suppressor of EMT, glycolysis, and tumor progression in others." (PMID 41463311, 2025). "For instance, in pancreatic cancer, SIRT6 facilitates the migration of pancreatic cancer cells and cytokine production by mediating deacetylation of histone H3K9." (PMID 41463311, 2025). "Compound 12q cellular activity was confirmed with a concentration-dependent decrease in acetylation of the Sirt6 substrate histone H3K9 in pancreatic cancer cell lines." (PMID 38474697, 2024). "SIRT6 has increasingly been recognized as a promising therapeutic target in pancreatic cancer, particularly due to its multifaceted role in modulating tumorigenesis, angiogenesis and responses to chemotherapy." (PMID 39682281, 2024). "SIRT6, recognized for its multifaceted role in tumorigenesis, angiogenesis and chemoresistance, has garnered increasing interest in pancreatic cancer research." (PMID 39682281, 2024). "Previous literature has expounded on the beneficial effects of upregulating SIRT6 in reducing glycolysis, epithelial‐mesenchymal transition, and distant metastasis in pancreatic cancer cells." (PMID 38967361, 2024). "Accumulating evidence suggests that the dual functions of SIRT6 as a regulator of metabolic processes and a guardian of genomic stability have positioned it as a key regulator in pancreatic cancer." (PMID 39682281, 2024). "We have identified a pyrrole-pyridinimidazole derivative 8a as a highly effective inhibitor of SIRT6 and clarified its anti-pancreatic-cancer roles." (PMID 37888452, 2023). "Recently, SIRT6 has been demonstrated to inhibit nuclear transcription of NF-κB and inactivate NF-κB to facilitate ferroptosis in pancreatic cancer, thereby exerting anti-tumor effects." (PMID 37153222, 2023). "We previously found that Ageladine A derivative 8a, a novel and highly effective inhibitor of SIRT6, can inhibit the activity of SIRT6 and has anti-pancreatic-cancer activity in vivo and in vitro." (PMID 37888452, 2023). "SIRT6 increased the levels of Ca2+-mobilizing second messengers and enhanced the expression of proinflammatory cytokines in pancreatic cancer, linking SIRT6 with a cancer cell proinflammatory phenotype and migratory propensity." (PMID 38116009, 2023). "This study showed that compound 8a is an effective SIRT6 inhibitor, and a potential drug candidate for pancreatic cancer treatment." (PMID 37542062, 2023). "On the other hand, SIRT6 has been shown to induce both the transcription and the secretion (also through post-translational modifications) of inflammatory cytokines in pancreatic cancer cells and in macrophages." (PMID 37047732, 2023). "In pancreatic cancer, the SIRT6 inhibitor quinazolinedione synergistically kills pancreatic cancer cells with gemcitabine." (PMID 35463332, 2022). "Quinazolinedione inhibits SIRT6 via competition with the peptide substrate, and sensitizes pancreatic cancer cells to gemcitabine and to olaparib." (PMID 35915188, 2022). "SIRT6 enhances cytokine production and migration in pancreatic cancer cells by regulating Ca2+ responses." (PMID 35422493, 2022).
pancreatic cancer (continued). "In contrast to most studies, KLF10, a transcriptional repressor, was found to transcriptionally activate SIRT6 in pancreatic cancer cells." (PMID 34702956, 2021). "On the other hand, we found that, consistent with our previous data in pancreatic cancer cells, SIRT6 overexpression increased, while SIRT6 silencing decreased, intracellular Ca2+ concentration in MDA-MB-231 cells." (PMID 33482921, 2021). "Although previous study reported that SIRT6 regulates the function of pancreatic cancer cells by modulating the NF‐AT activity." (PMID 33634990, 2021). "In our vector control pancreatic cancer cells, the levels of glycolytic enzymes were significantly elevated by LA but were suppressed by genetically overexpressing SIRT6." (PMID 34702956, 2021). "In pancreatic cancer cells, SIRT6-mediated increase of migration activity was mediated by Ca2+, and SIRT6 increased the expression of pro-inflammatory cytokines such as IL8 and TNF." (PMID 30524965, 2018). "SIRT6 promoted pancreatic cancer cell migration by inducing cytokines such as interleukin-8 and tumor necrosis factor in a Ca2+-dependent manner." (PMID 27777384, 2016). "Importantly, the antimetastatic capabilities of compound 11e were confirmed in both pancreatic cancer cell lines and mouse models, marking a significant milestone in the exploration of SIRT6 inhibitors for therapeutic application." (PMID 39682281, 2024). "Furthermore, it has been reported that SIRT6 can suppress the occurrence and development of pancreatic cancer." (PMID 38548549, 2024). "The discovery of potent SIRT6 inhibitors like compound 11e, with its remarkable selectivity and anti-metastatic properties, highlights the therapeutic potential of targeting SIRT6 in pancreatic cancer." (PMID 39682281, 2024). "Moreover, the expression levels of SIRT6 in pancreatic cancer tissues and cell lines have been shown to correlate inversely with patient prognosis, highlighting its role as a tumor suppressor." (PMID 39682281, 2024). "Ultimately, advancing our comprehension of SIRT6 could catalyze significant progress in the fight against pancreatic cancer, with the potential to improve outcomes for patients afflicted by this lethal disease." (PMID 39682281, 2024). "Overall, we demonstrate that 8a, a novel SIRT6 inhibitor, could be a promising potential drug candidate for pancreatic cancer treatment." (PMID 37542062, 2023). "Hence, developing highly effective SIRT6 inhibitors is important in improving the therapeutic effect of pancreatic cancer." (PMID 37542062, 2023). "when they identified SIRT6 as a pancreatic cancer suppressor." (PMID 36324577, 2022). "SIRT6 enhances Ca2+ responses, which promotes the migration ability of pancreatic cancer cells." (PMID 35463332, 2022). "Furthermore, JYQ-42 inhibited the activity of SIRT6 and had a killing effect on pancreatic cancer cells, and even a SIRT6 allosteric activator (MDL-800) was reported to have anticancer effects." (PMID 35915188, 2022). "However, in wild-type pancreatic cancer cells with sufficient amounts of SIRT6, the effect of LA in elevating SIRT6 was less efficient." (PMID 34702956, 2021). "In addition, consistent with a previous study by our group in pancreatic cancer cells, we found SIRT6 to increase the intracellular concentration of Ca2+, which is a known enhancer of PDH function, in MDA-MB-231 cells." (PMID 33482921, 2021). "SIRT6 suppressed pancreatic cancer through the control of Lin-28b." (PMID 33335996, 2020). "SIRT6 expression is lower in human pancreatic cancer than in healthy tissue." (PMID 27824900, 2016). "SIRT6 regulates Ca2+ responses to promote pancreatic cancer cell migration." (PMID 27777384, 2016). "However, another study showed that inhibiting SIRT6 reduced the viability of Capan-1 pancreatic cancer cells treated with gemcitabine, demonstrating the oncogenic potential of SIRT6." (PMID 27824900, 2016).